ORAI1 (ORAI calcium release-activated calcium modulator 1)
Diseases named in the same sentence as ORAI1 in open-access papers (continued):
Sharing a sentence is not in itself a finding about the gene and the disease.
amelogenesis imperfecta (2 papers, 2020 to 2022). Amelogenesis imperfecta (AI) represents a group of developmental conditions affecting the structure and clinical appearance of the enamel of all or nearly all the teeth in a more or less equal manner, and which may be associated with morphologic or biochemical changes elsewhere in the body. "In M-ABs, SOCE via the Orai1-Stim1 complex has been suggested to be the main calcium influx pathway, and patients with loss-of-function or null mutations in the STIM1 and ORAI1 genes present with a hypocalcified form of amelogenesis imperfecta." (PMID 36523561, 2022). "On the other hand, it is interesting to note that patients with loss-of-function mutations in STIM1 and Orai1 also display an amelogenesis imperfecta phenotype, indicating that dysregulation of SOCE has a direct effect on bone/enamel mineralization." (PMID 32350310, 2020).
anemia (2 papers, 2024 to 2025). A reduction in the number of red blood cells, the amount of hemoglobin, and/or the volume of packed red blood cells. "While hematological phenotypes (anemia, bleeding disorders) are observed in some TAM individuals, they are not typically observed in individuals with the G98S mutation in ORAI1." (PMID 39420094, 2024).
Anxiety (2 papers, 2020 to 2023). Intense feelings of nervousness, tension, or panic often arise in response to interpersonal stresses. "Mice that overexpressed STIM2 and ORAI1 in neurons exhibited reductions of anxiety-like behavior, including increases in exploration of the arena in the open field test and time spent on the open arms of the elevated plus maze." (PMID 32455839, 2020).
Arrhythmia (2 papers, 2018 to 2019). Any cardiac rhythm other than the normal sinus rhythm. "Furthermore, redistribution of STIM1 and ORAI1 from interior regions to the IDs resulted in augmented SOCE in myocytes from arrhythmia-prone (CPVT) hearts." (PMID 31308393, 2019). "Other recent works suggested that SOCE mediated by Orai1 interaction with STIM1 modifies heart rate by pacemaker stimulation, and plays a role in the initiation of arrhythmias in both atrial and ventricular myocytes." (PMID 29618985, 2018).
Arthritis (2 papers, 2019 to 2024). Inflammation of a joint. "Besides, immunohistochemical analysis of Orai1 demonstrated that resveratrol evidently reduced Orai1 expression and treatment of Orai1-vector or Orai-SiRNA also present their desired effects, which further identify the results of HE section, paw swelling and arthritis scores." (PMID 31426853, 2019).
basophilic leukaemia (2 papers, 2021 to 2022). "In addition, unlike Orai1, majority of the Orai2 is found in intracellular sites in rat basophilic leukemia (RBL-2H3) cells and the possibility that intracellular Orai2 could modulate Ca2+ influx has been suggested but the mechanism is not clear." (PMID 35126366, 2021).
brain injuries (2 papers, 2020). "In addition to revealing an essential Ca2+ entry mechanism for regulating synaptic plasticity and cognition, these results identify Orai1 channels as relevant molecular targets for the cognitive decline seen in neurodegenerative diseases and following brain injuries." (PMID 33264616, 2020). "Inhibiting CRAC channels with CM‐EX‐137 has been shown to decrease lesion size, brain hemorrhage, and improve neurological deficits while decreasing microglial activation, iNOS, Orai1, and STIM1 levels in an animal model of traumatic brain injury." (PMID 32525239, 2020).
cardiomyopathies (2 papers, 2020 to 2021). "Paradoxically, it is still unknown whether loss-of-function mutations in Stim1 or Orai1 result in heart defects or cardiomyopathies in humans." (PMID 32086252, 2020).
channelopathies (2 papers, 2024 to 2025). "In comparison, relatively few of these channelopathies have been documented to specifically affect the immune system, and these channelopathies are principally due to recessive or biallelic variants in ORAI1, STIM1, or the recently described regulatory protein CRACR2A." (PMID 39270020, 2024). "In-depth immunophenotyping and functional characterization, together with compelling clinical overlap with the non-immunological features seen in STIM1/ORAI1 channelopathies, such as ED and peripheral neuropathy, establish monoallelic missense variants in ITPR3 as a cause of syndromic CID." (PMID 39560673, 2025).
colorectal adenocarcinoma (2 papers, 2021 to 2024). The most common type of colorectal carcinoma. "Our results indicate that treatment of the colorectal adenocarcinoma cell lines HT‐29 and Caco‐2 with inanimate Lacticaseibacillus paracasei and Lactiplantibacillus plantarum results in a significant attenuation of SOCE due to downregulation of Orai1 and STIM1 expression." (PMID 38514909, 2024).
experimental autoimmune encephalomyelitis (2 papers, 2021). An autoimmune demyelinating disease of the central nervous system that is produced experimentally in animals by the injection of homogenized brain or spinal cord in Freund's adjuvant. "As with ORAI1, experimental autoimmune encephalomyelitis was ameliorated by inhibition of Kv1.3 alone, or of both Kv1.3 and KCa3.1, in CD4+ T-lymphocytes." (PMID 34639190, 2021). "Orai1 also modulates Th1 and Th17 responses in experimental autoimmune encephalomyelitis." (PMID 35126366, 2021).
fungal infection (2 papers, 2020). "The most severe form of fungal infection associated with CRAC channelopathy reported to date was a systemic C. albicans infection in a patient with ORAI1 p.L194P LOF mutation." (PMID 32609955, 2020). "Mutations of STIM1 and ORAI1 were also reported to affect patients with viral, bacterial, and fungal infections via abolishing the SOC influx and immune system." (PMID 33182378, 2020). "Taken together, we here show that STIM1 is a critical regulator of antifungal immunity by regulating the expression of cytokines and metabolic pathways in non‐pathogenic Th17 cells, which may explain the increased susceptibility of patients with STIM1 and ORAI1 mutations to fungal infections." (PMID 32609955, 2020).
hyperphosphatemia (2 papers, 2014 to 2021). Abnormally high level of phosphate in the blood. "In vascular smooth muscle cells, the effect of hyperphosphatemia on ORAI1/STIM1 expression and SOCE is suppressed by Mg2+ and the calcium-sensing receptor (CaSR) agonist Gd3+." (PMID 33804889, 2021). "Therefore, we may take ORAI1 polymorphism into account when prescribing calcium or non-calcium-based phosphate binder to CKD patients with hyperphosphatemia." (PMID 24745010, 2014).
ischemia (2 papers, 2021 to 2022). A hypoperfusion of the BLOOD through an organ or tissue caused by a PATHOLOGIC CONSTRICTION or obstruction of its BLOOD VESSELS, or an absence of BLOOD CIRCULATION. "The mechanism underlying harmful calcium influx caused by oxidative stress during ischemia is mediated by the ORAI calcium release-activated calcium modulator 1 (ORAI1) Ca2+ channel and store-operated calcium entry (SOCE)." (PMID 34055196, 2021). "Even though ER Ca2+ depletion represents an undisputed factor of neuronal cell injury, the modulation of the STIM1/ORAI1 complex during ischemia is still under scrutiny." (PMID 35163310, 2022).
kidney stone (2 papers, 2020 to 2021). "Other polymorphisms, such as in the CDH1, VEGF, IL18, IL1RA, MnSOD, ORAI1, and TAP genes, have also been reported to be associated with kidney stone recurrence." (PMID 33956883, 2021).
leukemia (2 papers, 2020 to 2022). A malignant (clonal) hematologic disorder, involving hematopoietic stem cells and characterized by the presence of primitive or atypical myeloid or lymphoid cells in the bone marrow and the blood. "We observed a significant increase in ORAI1 expression in KG1 cells and a significant decrease in U937 cells, in agreement with the observed Ara-C functional effects on SOCE in both leukemia cell lines." (PMID 35628366, 2022). "We first assessed the contribution of ORAI1 to SOCE in the U937 and KG1 leukemia cell lines." (PMID 35628366, 2022).
lung diseases (2 papers, 2015 to 2025). "However, further investigation will be needed to fully demonstrate a causal relationship between SPLUNC1, Orai1 and lung disease." (PMID 40589325, 2025). "It will be interesting to use this approach to look for altered Orai1 activation in other lung diseases." (PMID 40589325, 2025). "There are opposing views on how Orai1/SOCE should be modulated to treat lung disease." (PMID 40589325, 2025). "Auxora has been delivered intravenously and has shown significant improvements in COVID/ARDS patients, suggesting that inhibition of Orai1 may be beneficial for treating lung disease." (PMID 40589325, 2025). "Importantly, this established interaction between SPLUNC1 and Orai1 predicts that SPLUNC1 is much more than a biomarker of lung disease." (PMID 40589325, 2025). "Summary of changes in SPLUNC1, Orai1 and SOCE in different pulmonary diseases." (PMID 40589325, 2025).
lymph node metastasis (2 papers, 2014 to 2019). "Our results show that ORAI1 decreased with lymph node metastases, one of the first signs of metastatic spread." (PMID 31010205, 2019). "Multivariate analysis revealed that high expression of Orai1 was positively correlated with histological grade (p=0.019), T stage classification (p=0.029), lymph node metastasis (p=0.010) and advanced clinical staging (p=0.012)." (PMID 24797725, 2014).
metastatic melanoma (2 papers, 2014 to 2023). A melanoma that has spread from its primary site to another anatomic site. "We found that both STIM1- and Orai1-knockdown inhibited cell migration in metastatic melanoma cell lines." (PMID 24586666, 2014).
Miosis (2 papers, 2020 to 2022). Abnormal (non-physiological) constriction of the pupil. "Case 2 with the ORAI1 gene present with not only muscle weakness, stiffness and myalgia, but also a mild saddle nose deformity, pectus excavatum and miosis." (PMID 34908252, 2022).
myocardial infarction (2 papers, 2020 to 2022). Gross necrosis of the myocardium, as a result of interruption of the blood supply to the area, as in coronary thrombosis. "Transcriptional upregulation of Orai1-3 and reactivation of SOCE amplitude under stress condition was reported previously, including upregulation of SOCE activity after TAC and upregulation of Orai1 mRNA and protein expression after TAC and myocardial infarction." (PMID 32354146, 2020).
oropharyngeal cancer (2 papers, 2016 to 2021). Carcinoma, predominantly squamous cell, arising from the epithelial cells of the oropharynx. "According to their data Orai1 has been highly expressed in oral/oropharyngeal cancer and activates downstream molecule NFATc3 which proposes Orai1/NFAT axis to have importance on CSC in OPC." (PMID 34359786, 2021). "Our findings support the hypothesis that Orai1 is a novel molecular determinant of oral/oropharyngeal cancer progression." (PMID 27259269, 2016).
oropharyngeal squamous cell carcinoma (2 papers, 2016 to 2022). "For instance, it has been shown that ORAI1 and SOCE, through NFAT activation, promote stemness in oral/oropharyngeal squamous cell carcinoma." (PMID 35628366, 2022). "Here we report that intracellular level of Orai1 is increased in a stepwise manner during oral/oropharyngeal carcinogenesis and highly expressed in cancer stem-like cell (CSC)-enriched populations of human oral/oropharyngeal squamous cell carcinoma (OSCC)." (PMID 27259269, 2016).
osteopetrosis (2 papers, 2023 to 2025). Osteopetrosis, also known as marble bone disease, is a descriptive term that refers to a group of rare, heritable disorders of the skeleton characterized by increased bone density on radiographs. "Investigation of mice with global deletion of Orai1 revealed loss of multinucleated osteoclasts, that, intriguingly, did not lead to osteopetrosis: Instead, micro-computed tomography showed reduced cortical ossification and thinned trabeculae in Orai1-/- animals compared with controls." (PMID 37167218, 2023).
osteosarcoma (2 papers, 2020 to 2021). A usually aggressive malignant bone-forming mesenchymal neoplasm, predominantly affecting adolescents and young adults. "The deficiency in ORAI1 significantly reduced the dissemination of osteosarcoma U2OS cells, a finding that we propose is directly linked to the reduction in cell migration rate, in directional persistence, and in protrusion formation." (PMID 32313105, 2020). "Another study on highly metastatic osteosarcoma cell line U2OS reported that Ca2+ channel ORAI1 translocation to the leading edge was essential for formation of lamellipodia and cell directionality." (PMID 33802790, 2021). "By using an U2OS osteosarcoma cell line with high metastatic potential, proven by a xenotransplant in zebrafish larvae, we have studied the role of the plasma membrane Ca2+ channel ORAI1 in this process." (PMID 32313105, 2020).
renal carcinoma (2 papers, 2021). A carcinoma arising from the epithelium of the renal parenchyma or the renal pelvis. "Accumulating evidence demonstrates that the upregulation of Orai1/STIM1-mediated SOCE is associated with tumor progression and poor prognosis in multiple cancers including breast, lung, and renal cancer." (PMID 33386992, 2021). "Evidence have shown that STIM1 and ORAI1 regulate proliferation in different cancers, including brain, ovarian, pancreatic, nasopharyngeal, and renal cancers." (PMID 34155535, 2021).
Splenomegaly (2 papers, 2017 to 2022). Abnormal increased size of the spleen. "Stim1R304W/+Orai1+/− animals also manifested splenomegaly and prominent hyperplasia of the megakaryocytes, the precursor cells forming and releasing platelets into the bloodstream." (PMID 35805973, 2022).
Stroke (2 papers, 2020 to 2025). Sudden impairment of blood flow to a part of the brain due to occlusion or rupture of an artery to the brain. "The presently observed stimulation of ORAI1 and STIM2 could thus contribute to the known high risk of cardiac infarction and stroke in CKD patients." (PMID 32015442, 2020).
thyroid tumor (2 papers, 2021 to 2023). A benign or malignant neoplasm affecting the thyroid gland. "Surprisingly, an increased STIM1 gene expression but not ORAI1 was observed in the tumor adjacent normal tissue, compared to the normal thyroid tissue, indicating a possible role of STIM1 in the initiation of thyroid tumor formation." (PMID 34155535, 2021).
type 1 diabetes (2 papers, 2018 to 2021). "Here, we show that SOCE-related stromal interaction molecule 1 (STIM1) and Orai1 participate in inappropriate cellular Ca2+ homeostasis, augmenting agonist-induced small intestinal smooth muscle contraction and small bowel transit speed in a mouse model of type 1 diabetes." (PMID 34744757, 2021). "Similar to the expression in PBMCs from pregnant women, the average expression level of ORAI1, ORAI2 and ORAI3 were significantly up-regulated by type 1 diabetes." (PMID 30543678, 2018). "Our results show that in pregnancy and type 1 diabetes ORAI1-3 are up-regulated whereas STIM1 and 2 are down-regulated in pregnancy but only STIM2 in type 1 diabetes." (PMID 30543678, 2018). "Thus, we demonstrated that SOCE activity and SOCE-mediated contraction were significantly increased in SISM cells cultured in HG medium or in mice with type 1 diabetes and that altered SOCE activity and Orai1-BKCa channel interactions might contribute to accelerated gastrointestinal transit speed." (PMID 34744757, 2021).
viral infection (2 papers, 2017 to 2025). "This suggests that it may be specific to rare ORAI1 loss‐of‐function variants influencing the variability in COVID‐19 symptoms among patients, though the role of host cell calcium signaling during viral infections remains poorly understood overall." (PMID 41473684, 2025).
abdominal aorta coarctation (1 paper, 2022). "For example, choline can regulate the expression of key calcium-handling proteins, such as STIM1 and Orai1 and attenuate the angiotensin II-induced elevation of intracellular calcium, thereby alleviating the cardiac remodeling induced by abdominal aorta coarctation in rats." (PMID 36082183, 2022).
acute myeloid leukemia (1 paper, 2025). Acute myeloid leukemia (AML) is a group of neoplasms arising from precursor cells committed to the myeloid cell-line differentiation. "In acute myeloid leukemia (AML), Orai1–SOCE correlates with leukemic stem cell (LSC) proportion and drug resistance, indicating its utility as a biomarker." (PMID 40806720, 2025).
advanced heart failure (1 paper, 2017). Patients with advanced heart failure have severe limitations, experiences symptoms even while at rest and are mostly bedbound patients. "Although ORAI1 and STIM1 have been described in fibroblasts and human cardiac fibroblasts, their role in fibrosis in patients with advanced heart failure has not been described." (PMID 28126709, 2017).
airway hyperresponsiveness (1 paper, 2017). "Our data suggest that BPIFA1 deficiency in asthmatic airways promotes Orai1 hyperactivity, increased ASM contraction and airway hyperresponsiveness." (PMID 28165446, 2017).
allergic conjunctivitis (1 paper, 2024). "Besides pharmacological ORAI1 inhibitors, alternative strategies employed ORAI1-specific antibodies to reduce autoimmune response in ex vivo T cells from humans and mice, and the ORAI1-specific siRNA SYL116011 is used in preclinical studies for allergic conjunctivitis." (PMID 38516893, 2024).
allergic rhinitis (1 paper, 2023). Inflammation of the nasal mucous membranes caused by an IgE-mediated response to external allergens. "Recently, magnolol has been found to have anti-allergic effects on allergic rhinitis via the inhibition of ORAI1 (calcium release-activated calcium channel protein 1) and ANO1 (a calcium-activated anion channel 1) channels." (PMID 37214308, 2023).
anaplastic cancer (1 paper, 2021). "We show here that the protein level of STIM1 is higher in human follicular and anaplastic cancer cell lines, and that ORAI1 is higher in follicular cancer cell lines, compared with normal human thyroid primary cells." (PMID 34155535, 2021).
ataxia telangiectasia (1 paper, 2025). Ataxia-telangiectasia is the association of severe combined immunodeficiency (affecting mainly the humoral immune response) with progressive cerebellar ataxia. "SCID, CIDs, DiGeorge syndrome, Wiskott-Aldrich syndrome, Ataxia telangiectasia, Dyskeratosis congenita, ORAI-1 deficiency, CGD, X-linked Agammaglobulinemia, ALPS, STAT1 gain of function, CTLA-4 deficiency, GATA-2 deficiency, TRAPS, FMF, NEMO, TIM3, DOCK8, STAT2, STAT3, PIK3CD." (PMID 41049857, 2025).
autoimmune encephalitis (1 paper, 2021). Inflammation of the brain secondary to an immune response triggered by the body itself. "For example, knockout of STIM1 and STIM2 or ORAI1, key molecules controlling store operated Ca2+ entry, impaired the differentiation of Th1 and Th17 cells in vitro and in vivo, and protected mice from experimental autoimmune encephalitis." (PMID 34831261, 2021).
B-cell chronic lymphocytic leukemia (1 paper, 2019). "We reveal that GA101 triggered an intracellular Ca2+ increase by mobilizing intracellular Ca2+ stores and activating Orai1-dependent Ca2+ influx in non-Hodgkin lymphoma cell lines and primary B-Cell Chronic Lymphocytic Leukemia (B-CLL) cells." (PMID 30832225, 2019).
basal cell carcinoma (1 paper, 2021). A carcinoma involving the basal cells.
bone metastasis (1 paper, 2024). Transfer of a neoplasm from its primary site to bones. "The (CK+/STIM1+/ORAI1+) phenotype was correlated to bone metastasis (p = 0.034), while the (CK+/STIM1+/ORAI1–) to disease relapse (p = 0.049)." (PMID 38903530, 2024). "STIM1 and ORAI1 expression was related to disease recurrence and bone metastasis." (PMID 38903530, 2024).